MUC5B (mucin 5B, oligomeric mucus/gel-forming)
Diseases named in the same sentence as MUC5B in open-access papers (continued):
Sharing a sentence is not in itself a finding about the gene and the disease.
pulmonary fibrosis (continued). "Many individuals in the general population may carry the MUC5B risk allele without ever developing pulmonary fibrosis, so a positive test would have limited predictive value." (PMID 41465275, 2025). "The lack of association between the MUC5B rs35705950 minor allele and lung fibrosis in SSc suggests that this variant may be specific to IPF or the UIP pattern." (PMID 39768847, 2024). "Moreover, the question arises to what extent the expression of MUC5B contributes significantly to pulmonary fibrosis and whether drugs that suppress the expression of MUC5B are helpful." (PMID 39578767, 2024). "Specifically, we observed that MUC5B overexpression can significantly protect against inflammation, reduce the expression of inflammatory cytokines and growth factors, and mitigate the development of lung fibrosis in a bleomycin-induced model of lung fibrosis in mice." (PMID 39329706, 2024). "While the extant literature identifies the enhancement of lung fibrosis through MUC5B overexpression within the alveolar and distal bronchiolar compartments, our findings reveal that targeted overexpression within the proximal airways may impart protective advantages." (PMID 39329706, 2024). "The protective role of MUC5B overexpression observed in our study not only supports these previous findings but also provides new insights into the potential therapeutic benefits of modulating mucin levels to prevent or treat lung fibrosis and other related conditions." (PMID 39329706, 2024). "The implication of MUC5B in the development of pulmonary fibrosis proposes two hypotheses." (PMID 36672608, 2022). "Therefore, the MUC5B promoter polymorphism is a very specific predictive factor for the presence of pulmonary fibrosis as it is only associated with pulmonary fibrosis and not with other chronic respiratory diseases." (PMID 35651878, 2022). "While, idiopathic pulmonary fibrosis (IPF) has traditionally been considered a disease of the alveolus and lung matrix, the dominant environmental (cigarette smoking) and genetic (gain of function MUC5B promoter variant) risk factor primarily affect the distal airway epithelium." (PMID 34315881, 2021). "Among 67 respiratory conditions tested, 11 had significant associations including MUC5B locus (rs35705950) with increased risk of idiopathic fibrosing alveolitis OR 2.83, p=4.12 × 10−191; CRHR1 (rs61667602) associated with reduced risk of pulmonary fibrosis, OR 0.84, p=2.26 × 10−12." (PMID 34642702, 2021). "The results for MUC5B are less clear, since there is not a direct evidence in the literature of a link with oncogenic processes, but only with susceptibility and survival in pulmonary fibrosis through germline regulatory variants." (PMID 31156702, 2019). "Likewise, the human gain-of-function MUC5B promoter variant that causes overexpression of MUC5B in the distal airspace also does not appear to be sufficient to cause pulmonary fibrosis." (PMID 30560893, 2018). "A polymorphism in the MUC5B promoter region was strongly associated with familial and idiopathic pulmonary fibrosis (IPF; the most common IIP type), but it has not been found to be a susceptibility locus for SSc or SSc-associated interstitial lung disease (SSc-ILD)." (PMID 26792595, 2016). "However, the pulmonary fibrosis-associated MUC5B promoter variant does not influence the development of interstitial pneumonia in patients with systemic sclerosis or sarcoidosis." (PMID 25121989, 2014). "The low prevalence of the MUC5B variant rs35705950 suggests that it might not be the main risk factor for idiopathic pulmonary fibrosis in the Chinese population." (PMID 25121989, 2014). "The lack of an association with lung fibrosis in the context of autoimmune connective tissue diseases suggests that this MUC5B variant could not be related to share fibrotic mechanisms across CTD-ILD." (PMID 25121989, 2014).
pulmonary fibrosis (continued). "It has been reported that overproduction of mucin 5 B (MUC5B) or a decrease in TOLLIP exacerbates lung injury and pulmonary fibrosis." (PMID 40538533, 2025). "Lung fibrosis was induced in wild-type (WT/BLM) and human MUC5B rs35705950 transgenic (h-rs35705950-Tg/BLM) mice through continuous subcutaneous administration of bleomycin (BLM)." (PMID 39329706, 2024). "Aberrant ciliogenesis are found in the lung tissues of patients with usual interstitial pneumoniac (UIP)/idiopathic pulmonary fibrosis (IPF) and are closely related to the expression of Muc5b." (PMID 37999562, 2023). "Mice with BLM-induced lung fibrosis treated with anticorisin mAtb showed low plasma and BALF levels of osteopontin and MUC-1, reduced BALF MUC5B level, decreased number of apoptotic lung cells, and reduced cleavage of caspase-3." (PMID 35322016, 2022). "In addition, promoter polymorphisms within MUC5B (rs35705950) are the most important genetic risk factor for both familial and sporadic IPF, being present in about 40% of patients and 10% of controls, with both a predictive and prognostic role in lung fibrosis." (PMID 35328744, 2022). "MUC5B rs35705950, but not FCGR2A rs1801274, increases susceptibility to clinical pneumonia, especially to idiopathic pulmonary fibrosis, in both the Caucasian and Asian populations." (PMID 32252656, 2020). "Although Muc5b transgenic mice do not appear to spontaneously develop pulmonary fibrosis, they are more responsive to bleomycin." (PMID 30560893, 2018). "MUC5B had a similar expression profile to MUC1, being most elevated in the sigmoid colon, but is a secreted polymeric mucin that can be dysregulated in the lung of subjects with idiopathic pulmonary fibrosis." (PMID 22829946, 2012). "KL-6 levels were higher in idiopathic pulmonary fibrosis (IPF) than fibrotic hypersensitivity pneumonitis (fHP) (105.6 ng/mL vs. 65.87 ng/mL; p=0.0409), in patients who died (109.8 ng/mL vs. 68.6 ng/mL; p=0.022), and in the MUC5B (rs35705950) GT/TT genotype (85.07 ng/mL vs. 65.58 ng/mL; p=0.019)." (PMID 41049336, 2025). "This is the case of MUC5B rs35705950 mutation, ABCA3 mutation and the mutation in surfactant proteins, which were associated in our study with a predominant atypical pattern of pulmonary fibrosis, but not the classical UIP pattern at the time of diagnosis." (PMID 33922858, 2021). "The lack of an association between the MUC5B rs35705950 T allele and SSc related ILD suggest that this polymorphism does not associate with lung fibrosis in general, but might be specific for either IPF or UIP." (PMID 23940607, 2013). "However, biomarkers like MUC5B and MMP-7 in bronchoalveolar lavage (BAL) fluid or serum are not specific and cannot be used alone for the diagnosis of pulmonary fibrosis, whereas metabolites in the blood have the potential to renew hope." (PMID 39175820, 2024).
idiopathic pulmonary fibrosis (77 papers, 2012 to 2026). Idiopathic pulmonary fibrosis (IPF) is a nonneoplastic pulmonary disease that is characterized by the formation of scar tissue within the lungs in the absence of any known cause. "This is especially interesting given that the same MUC5B variant is the strongest known risk factor for idiopathic pulmonary fibrosis (IPF), which shares many similarities with RA-ILD." (PMID 31709258, 2019). "The MUC5B promoter variant rs35705950 (a G/T transversion), located within a −3 kb enhancer region, undergoes chromatin accessibility and epigenetic reprogramming in idiopathic pulmonary fibrosis (IPF)—a disease linked to lung cancer risk." (PMID 40655139, 2025). "A study of the Western population revealed the MUC5B promoter variant rs35705950 as a genetic risk factor for developing RA-ILD, particularly in those with the usual interstitial pneumonia (UIP) pattern." (PMID 38203796, 2024). "Sequence variants in genes for surfactant proteins (SFTPC, SFTPA1, SFTPA2, ABCA3), polymorphisms in MUC5B or TOLLIP, and mutations in telomere genes (TERT, TERC, PARN, and RTEL1) are associated with an increased risk of idiopathic pulmonary fibrosis (IPF)." (PMID 36864460, 2023). "Furthermore, a gain-of-function promoter variant (rs35705950) in the mucin 5B (MUC5B) gene is observed to be associated with RA-ILD, more specifically with the usual interstitial pneumonia (UIP) pattern." (PMID 39001320, 2024). "The presence of the MUC5B variant was observed in 50% of patients with RA disease, with the strongest association with rheumatoid arthritis interstitial lung disease (RA-ILD) (especially in patients with usual interstitial pneumonia—UIP and fibrosing hypersensitivity pneumonitis—HP)." (PMID 41010839, 2025). "Previous studies have identified genetic variants associated with mucin gene expression (eQTL) that are located within or near MUC5AC (in asthma) and MUC5B (in idiopathic pulmonary fibrosis, IPF)." (PMID 37352370, 2023).
asthma (72 papers, 2007 to 2025). "The mucin MUC5B is usually associated with respiratory health, and this was less abundant in bronchiectasis and CF sputum samples compared with asthma, COPD, and control samples." (PMID 40876742, 2025). "Our results further demonstrate that EPO-BM-MSCs suppress the expression of mucin markers (MUC5AC and MUC5B) in asthmatic lungs, which is critical for alleviating airway obstruction—a hallmark of severe asthma." (PMID 41023810, 2025). "Associations have also been found between variants of mucin-encoding genes (MUC5AC and MUC5B) and the risk for asthma, where the variants are predicted to cause increased mucin production." (PMID 33255348, 2020). "More recently, analysis of MUC5B glycoforms in children with asthma showed that the low-charge glycoform was most associated with acute asthma." (PMID 30154090, 2018). "In mouse models of asthma, airway epithelial cells show upregulation of Muc5b message in association with mucus-cell hyperplasia." (PMID 27669173, 2016). "Given that glandular secretion in response to SubP is defective in CF, a speculation is that SubP-mediated secretion in CF might be associated with enhanced muc5AC to muc5B secretion ratios, effectively mimicking asthma." (PMID 30081920, 2018). "Similarly, examining how acute and/or repeated applications of neuropeptides affect expression of mucins (e.g., muc5AC, muc5B) in asthma, COPD, and CF would reveal a potentially causative role for neuropeptides in airway mucus phenotypes." (PMID 30081920, 2018). "Analysis of goblet cell profiles determined a strong enrichment of MUC5B expression, ~340% more in samples from individuals with asthma than in healthy samples." (PMID 40399607, 2025). "In the lungs of individuals with asthma, there is a shift from MUC5B to MUC5AC as the predominantly secreted mucin which has been shown to impair mucociliary clearance (MCC) and increase airway mucus plug formation." (PMID 40849510, 2025). "As anticipated, we observed increased MUC5AC and MUC5B mucin peptides associated with EVs isolated from COPD and asthma BW specimens." (PMID 40553562, 2025). "Taken together, findings from the asthma and COPD literature converge on a model in which MUC5AC is more closely linked to disease pathology, whereas MUC5B plays a comparatively lesser role." (PMID 41561092, 2025). "Suppression of excessively secreted MUC5AC and MUC5B is expected to alleviate airway narrowing and asthma symptoms." (PMID 40869396, 2025). "This was confirmed in our second cohort of participants, with samples from individuals with severe asthma exhibiting higher MUC5B expression and a tendency toward increased MUC5AC expression." (PMID 40399607, 2025). "A characteristic of asthma is the altered MUC5B:MUC5AC ratio, with MUC5AC being more predominant in asthmatic sputum." (PMID 41303221, 2025). "In summary, our L1000CDS2 analysis predicted that lovastatin perturbs gene networks involved in adult asthma via effects on MUC5B expression." (PMID 37241840, 2023). "Mucus secretion was also reduced, and the downregulation of two key mucins, MUC5AC and MUC5B, which are integral components of mucus dysfunction in asthma, was observed in the PP121-treated mice." (PMID 37936054, 2023). "In asthma, MUC5B levels decreased or remained the same, while other types of mucin levels were increased significantly." (PMID 35292003, 2022). "An interesting clinical study performed in patients with severe asthma showed overexpression of CEACAM6 in hyperplastic/metaplastic EC strictly correlated with MUC5B, thus suggesting an up-regulation of this glycoprotein in injured metaplastic cells." (PMID 35328744, 2022). "The most influential nodes (Fn1, Igf1, Ccl2, C3, Timp1, Cxcl12, Ccl4, Ccr2, Spp1, C3ar1, Cat, Cyp2e1, Muc5ac, Muc5b) were selected for further validation in the OVA-induced asthma and post-asthmatic fibrosis murine model." (PMID 35625754, 2022).
asthma (continued). "MUC5B is crucial for the innate defense of the lungs’ and predominates in healthy human lungs; its levels in asthma either remain stable or decrease." (PMID 36012669, 2022). "Increased Gal-3 in mice with TIMPKO, murine asthma model is associated with decreased MUC5AC and MUC5B levels, while inhibition of Gal-3 results in increased MUC5AC and MUC5B in a lung epithelial cell line." (PMID 34221020, 2021). "Previous studies found that the assembly of cilia is remarkably decreased but the secretion of mucins (encoded by MUC5AC and MUC5B) is increased in COPD, asthma, IPF, and cystic fibrosis." (PMID 34149803, 2021). "In humans with asthma, MUC5B decreases in many patients, and lower MUC5B levels are associated with worsened disease." (PMID 33431872, 2021). "Phenotype-related differences are also observed in mucins, as MUC5AC and MUC5B overexpression is present in all asthma phenotypes but with enhanced increases in mixed and neutrophilic asthma." (PMID 34248677, 2021). "In bronchoalveolar lavage (BAL) fluid from patients with mild-to-moderate asthma, TCEP rapidly depolymerizes MUC5AC and MUC5B, demonstrating the presence of targets in asthma patients even under stable disease conditions." (PMID 33431872, 2021). "The polymeric mucins, Muc5ac and Muc5b are primarily responsible for mucus production in mouse models of asthma." (PMID 35386975, 2021). "Although our study datasets didn’t define the severity level of asthma, epithelial MUC5B repression was observed in mild-moderate asthma by other studies." (PMID 32770056, 2020). "In asthma, the proportion of MUC5B relative to MUC5AC often decreased along with the expression of a low-charge form of MUC5B." (PMID 32411147, 2020). "In mice, excess mucus production is a cardinal feature of asthma that is regulated by 2 polymeric mucins: Muc5ac and Muc5b." (PMID 32477356, 2020). "The expression of MUC5B was elevated in OVA-induced mouse asthmatic airways, and large amounts of glandular MUC5B extracellular mucus were observed in patients with mild asthma." (PMID 31692453, 2019). "Due to the unstable expression of MUC5B, its contribution to mucus dysfunction in asthma requires further exploration." (PMID 31692453, 2019). "Elevated levels of MUC5AC and MUC5B have been reported in asthma patients, and elevated MUC5B levels have been observed in patients with chronic obstructive pulmonary disease (COPD)." (PMID 31514468, 2019). "In fatal asthma, the low-charge glycoform of MUC5B was enriched in the viscid mucus plugging the airways." (PMID 30154090, 2018). "Another study identified MUC5B as the predominant mucin in healthy secretions, while MUC5AC concentration increased and MUC5B decreased in individuals with asthma, including those in exacerbation." (PMID 29186064, 2017). "Further studies would benefit from more information regarding viral exposure during acute asthma exacerbation and from measuring the concentration of MUC5AC and MUC5B during an acute asthma exacerbation and at recovery in the same patient." (PMID 28716644, 2017). "MUC5B concentrations showed less variation, with 238.5, 208.4 and 165.9 μg/mL in control subjects, those with stable asthma, and those with acute asthma, respectively." (PMID 28716644, 2017). "Recent findings by Bonser et al14 have demonstrated that altered mucin composition (increased MUC5AC, reduced MUC5B) dramatically impairs mucus transport in asthma, likely contributing to the viscous plugs seen in acute disease." (PMID 28716644, 2017). "Herein, we review our current understanding of the role of MUC5AC and MUC5B in mucus dysfunction in asthma." (PMID 29186064, 2017). "Altered MUC5AC and MUC5B gene expression is consistently observed in both asthma models and individuals with disease." (PMID 29186064, 2017).